COL6A3 (collagen type VI alpha 3 chain)
Diseases named in the same sentence as COL6A3 in open-access papers (continued):
Sharing a sentence is not in itself a finding about the gene and the disease.
ovarian carcinoma (12 papers, 2014 to 2025). A malignant neoplasm originating from the surface ovarian epithelium. "The host gene of circCOL6A3_030 was COL6A3 (collagen VI alpha 3), encoding the α-3 chain of type VI collagen, which has been found to participate in the tumor malignant processes in gastric, pancreatic, and ovarian cancer." (PMID 34595992, 2021). "Furthermore, COL6A3 was identified to be overexpressed in pancreatic and ovarian cancer, which was associated with the poor differentiation of tumor cells." (PMID 24765172, 2014). "In 2003, Serial Analysis of Gene Expression (SAGE) sequencing of ovarian cancer cells with acquired resistance to cisplatin showed a 12-fold increase in COL6A3 mRNA in therapy-resistant cells compared with the parental lines." (PMID 41228242, 2025). "First, we found COL6A3 exosomes promoting tumor dissemination and metastasis in epithelial ovarian cancer." (PMID 39125689, 2024). "Our study explores the role of cancer-derived extracellular exosomes (EXs), particularly focusing on collagen alpha-3 (VI; COL6A3), in facilitating tumor dissemination and metastasis in epithelial ovarian cancer (EOC)." (PMID 39125689, 2024). "We found that the loss of CTGF in epithelial ovarian cancer cells is associated with modifications on the expression of several genes associated with the ECM, including LAMC2 SPP1, SV2A, RELN, COL6A3, and COL4A6." (PMID 37835529, 2023). "Sherman found that the expression of COL6A3 was correlated with cisplatin resistance in ovarian cancer cell lines." (PMID 31895688, 2020). "Recent studies have demonstrated that COL6A3 was up-regulated in gastric, pancreatic, and ovarian cancers." (PMID 28105922, 2016). "Ovarian cancer cells resistant to cisplatin show a potent induction of the Col6a3 gene and in vivo, high grade tumours express higher levels of Col6a3 than low grade tumours." (PMID 24498316, 2014). "Gene expression analysis of the ovarian cancer cell line A2780 after dose escalation and the development of acquired resistance to oxaliplatin and cisplatin revealed a 62-fold increase in COL6A3 transcript levels compared with therapy-sensitive clones, supporting the original reports." (PMID 41228242, 2025). "COL6A3 has also been reported to be related to oxaliplatin resistance in ovarian cancer cells." (PMID 36167487, 2022). "In ovarian cancer cell lines resistant to Cis, overexpression of COL6A3 has been observed." (PMID 24804215, 2014). "Our recent study showed COL6A3 could be detected in culture media and is abundant in primary ovarian cancer tissues, disseminated metastatic omentum tissues, EOC spheroids, and MSC-OCSPCs, which appear to possess the new function of promoting EOC in EMT, stemness, tumor growth, and metastasis." (PMID 39125689, 2024). "We found that COL6A3 is expressed in aggressive ES2 derivatives, SKOV3 overexpressing COL6A3 (SKOV3/COL6A3), and mesenchymal-type ovarian carcinoma stromal progenitor cells (MSC-OCSPCs), as well as their EXs, but not in less aggressive SKOV3 cells or ES2 cells with COL6A3 knockdown (ES2/shCOL6A3)." (PMID 39125689, 2024). "Similar to the mesenchymal subtype from the original TCGA study of ovarian cancer, S‐ECM shows upregulation of genes such as COL5A2, COL1A1, COL3A1, THBS2, COL11A1, COL6A3, and MMP2 that are involved in epithelial‐to‐mesenchymal transformation (EMT) processes, metastasis, and chemoresistance." (PMID 36637997, 2023). "There are no reports to date on the relationship between COL6A3 and the metastasis of ovarian cancer." (PMID 31895688, 2020).
pancreatic cancer (10 papers, 2014 to 2025). "We found that Ccn1‐deficient pancreatic cancer cells exhibit reduced expression of collagens, including Col4a1, Col4a2, Col5a1, Col6a1, Col6a2, Col6a3, and Col8a1." (PMID 40287974, 2025). "Differential splicing of COL6A3, and in particular of exon 4, has previously been associated with pancreatic cancer and colon cancer, though in these studies it was inclusion as opposed to exclusion of exon 4 that associated with the disease phenotype." (PMID 24647608, 2014). "Similarly, mRNA levels of Col5a1, Col6a1, Col6a2, Col6a3, and Col8a1 were significantly reduced in Ccn1‐deficient pancreatic tumors, while Col4a1 and Col4a2 were unaffected." (PMID 40287974, 2025). "COL6A3 functions in tumorigenesis and progression of cholangiocarcinoma through the E2F1/LMCD1-AS1/miR-345-5p/COL6A3 axis and serves as prognostic factor for pancreatic cancer." (PMID 35036081, 2022). "A bulk of collagen associated genes have previously been proved to be upregulated and participated in the process of tumor development, such as COL6A3 in pancreatic cancer." (PMID 34319913, 2021). "The splicing change of the exon 6 of COL6A3 has been reported previously in colon, bladder, prostate and pancreatic cancers tissues compared to normal tissues, indicating that the splicing change may play a role in multiple cancer types." (PMID 32503434, 2020). "COL6A3, an ECM protein, has been identified as the clinically relevant collagen in colorectal, ovarian, and pancreatic cancer." (PMID 28415608, 2017). "A high level of expression of COL6A3 has been observed in pancreatic tumors, where it was correlated with negative prognostic factors." (PMID 32934754, 2020). "In addition, three hub genes (SPARC, COL6A3, and FBN1) may also play a vital role in the microenvironment of pancreatic cancer through the regulation of tumor-infiltrating immune cells, suggesting they could serve as potential therapeutic targets for the modulation of the antitumor immune response." (PMID 32934754, 2020). "The other proteins in these pathways were members of the families of interleukin (ITGA2, ITGB6), laminin (LAMC2), and collagen (COL1A1/2, COL6A3), together with cartilage oligomeric matrix protein (COMP), whose role in pancreatic cancer has not yet been clarified." (PMID 33194391, 2020).
colon cancer (9 papers, 2006 to 2026). "COL6A3 was associated with metastasis potential of single cell-derived progenies of colon cancer cell line SW480." (PMID 26338966, 2015). "The COL6A3 expression was also associated with recurrence status of colon cancer patients (p = 0.006), as revealed by Smith Colorectal dataset." (PMID 26338966, 2015). "Despite all these observations, the diagnostic and prognostic value of COL6A3 in colon cancer remains elucidative." (PMID 26338966, 2015). "Finally we revealed that collagen alpha-3(VI) chain (COL6A3) was a potential diagnostic and prognostic biomarker of colon cancer." (PMID 26338966, 2015). "Interestingly, stroma-positive COL6A3 was significantly associated with poor prognosis of colon cancer patients (Log-rank test = 4.331, p = 0.0374)." (PMID 26338966, 2015). "A mutated COL6A3 gene could predict better survival of colon cancer patient." (PMID 26338966, 2015). "The research successfully identified and validated the role of COL6A3 as a potential biomarker and putative target modulated by Embelin in colon cancer." (PMID 41704606, 2026). "Data from TCGA showed that compared with normal tissues, COL6A3 expression level is higher in colon cancer tissues." (PMID 33947841, 2021). "We analyzed the correlation between the mRNA expression of COL6A3 and the clinicopathological parameters of colon cancer patients by re-analyzing selected Oncomine datasets containing more than 100 cases." (PMID 26338966, 2015). "To address the prognosis significance of COL6A3 in CRC, we performed Kaplan-Meier survival curve analysis of colon cancer patients with different COL6A3 mRNA level." (PMID 26338966, 2015). "We performed a data mining analysis of the mRNA expression of COL6A3 in colon cancers using the Oncomine gene expression array datasets." (PMID 26338966, 2015). "To further evaluate COL6A3 expression in colon cancer, we performed an immunohistochemistry (IHC) analysis of COL6A3 expression using a commercial tissue microarray (TMA) containing an independent cohort of CRC (90 cases) samples." (PMID 26338966, 2015). "First, we analyzed the correlation of stromal COL6A3 expression with the survival of colon cancer patients." (PMID 26338966, 2015). "In colon cancer, the upregulation of COL6A3 gene and its alternatively splicing has been observed." (PMID 26338966, 2015). "The AS of CALD1, COL6A3, FN1, MAST2, LGR5 and ITGB4 were previously validated in colon cancer using RT-PCR24, while CLSTN1, AUP1, CTNND1, CALD1 and COL6A3 were shown to exhibit tumour-specific splice variants in colon, bladder and prostate cancers." (PMID 28592875, 2017). "The Western blot assay indicated that FLNC, COL6A3, COL4A1 and SPON2 were abundantly expressed in the colonic fibroblasts instead of the colon cancer epithelial cells." (PMID 26338966, 2015). "We chose COL4A1, COL6A3, spondin-2 (SPON2) and FLNC for further analysis for their high abundance (peptide count), high “fold change” and less chances being identified in colon cancer cell lines." (PMID 26338966, 2015).
osteosarcoma (8 papers, 2021 to 2025). A usually aggressive malignant bone-forming mesenchymal neoplasm, predominantly affecting adolescents and young adults. "In line with the heterogeneity of osteosarcoma, we found subpopulations of osteosarcoma cells that highly expressed COL6A1, COL6A3 and MIF and were closely associated with lung metastasis." (PMID 35463309, 2022). "PODN was regarded as a potential biomarker for the diagnosis and prognosis of osteosarcoma, ACTA2, COL6A1, FAP, OLFML2B and COL6A3, can be used as potential prognostic indicators for osteosarcoma." (PMID 34273970, 2021). "In the case of module 3 genes associated with osteosarcoma, eight are found in COSMIC (LUM, COL6A3, TNC, CALU, COL16A1, OMD, ITGB5, and DPSYL3), and two (CDH11 and OMD) are oncogenes found in OncoKB." (PMID 34570764, 2021). "Additionally, genes like COL6A1, COL6A3, and MIF were associated with lung metastasis, indicating that a highly invasive subcluster in osteosarcoma correlated with a poor prognosis." (PMID 39324133, 2024). "Interestingly, AKT phosphorylation was shown to be similarly affected upon COL6A3 siRNA-mediated silencing in osteosarcoma cells, also displaying a marked deregulation upon COL6A1 and COL6A2 modulation in bladder cancer cells." (PMID 37505240, 2023). "Finally, it was determined that PODN has functional relevance in osteosarcoma and additional genes (ACTA2, COL6A1, FAP, OLFML2B and COL6A3) have prognostic significance for osteosarcoma." (PMID 34273970, 2021). "Furthermore, ACTA2, COL6A1, FAP, OLFML2B and COL6A3, can be used as prognosis biomarkers for osteosarcoma." (PMID 34273970, 2021). "In addition, somatic mutations in COL6A3 and ITGB5 have been documented for osteosarcoma samples in COSMIC." (PMID 34570764, 2021). "Moreover, upon inhibition of COL6A3, the expression of the PI3K/AKT pathway-related markers changed significantly, suggesting a crucial role for COL6A3 in modulating various aspects of the progression of osteosarcoma, which would provide a potentially effective treatment for osteosarcoma." (PMID 37681913, 2023). "TNC, LUM, COL12A1, COL6A3, and BGN are among the DEPs that differentiate the chondroblastic group from other subtypes of osteosarcoma." (PMID 37681913, 2023). "The fact that COL6A3, COL5A2, TNC, and ITGB5 which are highly activated here and part of the focal adhesion-PI3K-Akt signaling axis implies that they are central to osteosarcoma and not simply tissue specific activation." (PMID 34570764, 2021).
bladder cancer (7 papers, 2019 to 2025). "After transient silencing of COL6A3 using gene-specific siRNAs, bladder cancer cell lines expressed less TGF-β and exhibited less SMAD2/3 activity, indicated by their hypophosphorylation." (PMID 41228242, 2025). "In bladder cancer, we have a better mechanistic understanding, where COL6A3 activates the transforming growth factor β (TGF-β) pathway." (PMID 41228242, 2025). "In contrast, COL6A3 has been proved to be highly expressed in bladder cancer tissues and cells." (PMID 36167487, 2022). "COL6A3 silencing suppresses the expression of MMP-2, MMP-9, and vimentin, then participates in the process of inhibiting EMT of bladder cancer cells." (PMID 35774273, 2022).
congenital muscular dystrophy (7 papers, 2017 to 2025). A muscular dystrophy that is characterized by diminished muscle tone (hypotonia), progressive muscle weakness and degeneration (atrophy), abnormally fixed joints, spinal rigidity, and delays in reaching motor milestones such as sitting or standing unassisted. "COL6A3 protein deficiency in mice leads to muscle and tendon defects similar to those seen in human collagen VI congenital muscular dystrophy." (PMID 32759223, 2020). "Mutations in the COL6A1, COL6A2 and COL6A3 genes result in congenital muscular dystrophy, arguing that collagen is critical for skeletal muscle development and function." (PMID 28755659, 2017). "In addition, mutations in COL6A1, COL6A2 and COL6A3 genes were considered causal mutations for congenital muscular dystrophy, a disease that affects connective and muscular tissue in humans." (PMID 32379844, 2020). "Causative variants in COL6A1, COL6A2 and COL6A3 genes result in skeletal muscle disorders, collectively called “collagen VI myopathies”, which represent a common type of congenital muscular dystrophy (CMD), identified in 20.24% of Italian CMD patients." (PMID 41154655, 2025). "Collagen VI-related dystrophies are a subtype of congenital muscular dystrophy caused by pathogenic variants in COL6A1, COL6A2 or COL6A3 genes affecting skeletal muscles and connective tissue." (PMID 33750322, 2021).
COVID-19 (7 papers, 2022 to 2024). A disease caused by infection with severe acute respiratory syndrome coronavirus 2. "We successfully identified the shared 6 candidate gene signatures (RRM2, EGF, TMEM252, RARRES1, COL6A3, CUBN) between COVID-19 and AKI." (PMID 37789254, 2023). "The results revealed that 6 key gene signatures (RRM2, EGF, TMEM252, RARRES1, COL6A3, CUBN) were recognized to have great influences on COVID-19 and AKI." (PMID 37789254, 2023). "Importantly, several unreported elevated proteins in patients with COVID-19, such as RBP2 and BST2, which show anti-microbial activity, along with proteins involved in extracellular matrix remodeling, including MATN2 and COL6A3, were identified." (PMID 37047248, 2023).
Hepatic fibrosis (6 papers, 2014 to 2024). The presence of excessive fibrous connective tissue in the liver. "Importantly, PI3K-AKT and focal adhesion-related proteins, such as PDGFRβ, PIKR3R1, ITGB5, COL1A1, COL6A1, COL6A3, and LAMA5, are mainly associated with liver fibrosis." (PMID 38469403, 2024). "Collagen VI (COL6A1, COL6A2, and COL6A3) genes, but not COL1A1, have been associated with liver fibrosis." (PMID 38041174, 2023). "Therefore, our study investigated the role of COL6A1, COL6A2, COL6A3, and COL1A1 expressions on liver fibrosis in BA patients in Indonesia." (PMID 38041174, 2023).
cervical cancer (5 papers, 2020 to 2024). A primary or metastatic malignant neoplasm involving the cervix. "Dysregulated expression of COL6A3 has been observed in several cancers, including cervical cancer and pancreatic adenocarcinoma." (PMID 38841188, 2024). "CCL21 was found to be significantly downregulated as compared to COL6A3 as shown in, and all these genes behaved similarly as seen in the microarray data and our study is in accordance with other published reports of cervical cancer." (PMID 33829064, 2021). "The candidate genes SPP1, FOXM1, LYN, COL6A3, CCL21, TTK and MELK at mRNA level, emerge as promising candidate markers for cervical cancer prognosis and also emerge as potential therapeutic drug targets." (PMID 33829064, 2021). "Collagen members, including COL6A3, COL5A1, and COL8A1, act as oncogenes in the progression of different types of cancer and are highly correlated with poor prognosis in cervical cancer patients." (PMID 32523603, 2020).
diabetes (5 papers, 2020 to 2023). "The major adipocyte-derived secretory protein COL6A3 is up-regulated in metabolic syndrome disorders such as diabetes." (PMID 35068329, 2022). "While we speculate that alteration of TIMP2 and COL6A3 in human DPN results in ECM remodeling, further investigation will determine how these changes impact nerve function in diabetes." (PMID 32787975, 2020).
pancreatic adenocarcinoma (5 papers, 2021 to 2025). "The COL6A3 protein is described in tissue as well as serum, and is a potential prognostic factor for pancreatic adenocarcinoma." (PMID 36765644, 2023). "AS events of FGFR-2, SPAR, COL6A3 in pancreatic adenocarcinoma have also been previously reported 30-32, and an increase in AS of the KLF6 cancer suppressor gene is associated with pancreatic adenocarcinoma prognosis and tumour grade 33." (PMID 33976726, 2021). "TCGA analysis of TGF-β target genes (e.g., COL1A1, COL3A1, COL5A2, COL6A1, COL6A3, TIMP1, and CTGF) further identified overactivation of TGF-β signaling pathway in a broad spectrum of solid tumors, in particular in breast invasive carcinoma and pancreatic adenocarcinoma tissues." (PMID 37328484, 2023).
pancreatic ductal adenocarcinoma (5 papers, 2015 to 2024). An infiltrating adenocarcinoma that arises from the epithelial cells of the pancreas. "COL6A3 protein and mRNA were significantly upregulated in pancreatic ductal adenocarcinoma (PDA) and the diagnostic and prognostic value of circulating COL6A3 in PDA had been addressed." (PMID 26338966, 2015). "Analysis of TCGA PanCancer RNA sequencing data revealed that, like in sarcomas, COL6A1, COL6A2, and COL6A3 are highly expressed in pancreatic ductal adenocarcinoma (PDAC)." (PMID 38652549, 2024). "And COL6A3 was highly expressed in pancreatic ductal adenocarcinoma (PDA) tissue." (PMID 31286980, 2019).
breast tumor (4 papers, 2008 to 2023). "We note that ColVI is special in the sense that a C-terminal soluble cleavage product of COL6A3 chain (endotrophin (ETP)) was found to augment breast tumor growth." (PMID 36191045, 2022). "In total 4063 breast tumor samples, we found only 239 point mutations were recorded at these ECM genes in these tumors (all frequencies are less than 1% except COL6A3 was 4%)." (PMID 29541388, 2018). "Kmplot was used to investigate the relevance of Col6a3 expression in human breast tumors." (PMID 36901727, 2023). "Our module showed the breast tumor specific co-expression between PDGFRL and collagens COL3A1, COL5A2 and COL6A3." (PMID 18366601, 2008).
hepatocellular carcinoma (4 papers, 2014 to 2024). A malignant tumor that arises from hepatocytes. "In the present study, a microarray meta-analysis was performed to identify that COL6A3 was frequently overexpressed in hepatocellular carcinoma tissues, indicating that an increased expression of COL6A3 was associated with the carcinogenesis of GC." (PMID 24765172, 2014). "Co-treatment with KPA also decreased the expression of genes, regulating the progression of fibrosis (e.g., COL6A3, AEBP1, SPARC, TNC, LAMB1, BGN) and hepatocellular carcinoma (e.g., COL4A1, COL4A2, TUFT1, VCAN, NID1)." (PMID 39404414, 2024).